SFRP5 (secreted frizzled related protein 5)
Diseases named in the same sentence as SFRP5 in open-access papers (continued):
Sharing a sentence is not in itself a finding about the gene and the disease.
cardiac diseases (2 papers, 2022 to 2025). "Our study demonstrated that the SFRP5 rs780369540 polymorphism was strongly associated with cardiac disease risk, with the C allele appearing linked to lower disease susceptibility and the T allele linked to adverse cardiac markers." (PMID 41465371, 2025). "We hypothesized that the SFRP5 rs4808793 single-nucleotide polymorphism contributes to cardiac disease susceptibility through modulating Wnt and JAK/STAT molecular pathways, and that carriers of the risk genotype display distinct biochemical and molecular profiles compared to other genotypes." (PMID 41465371, 2025). "BMI, SFRP5, WNT5a, and JAK have been confirmed to be independent predictors of cardiac disease, highlighting their potential as biomarkers for risk stratification." (PMID 41465371, 2025). "Larger studies are needed to validate the SFRP5 single-nucleotide polymorphism (rs780369540) in broader populations and to discuss the mechanistic association between SFRP5 levels/SNP (rs780369540), JAK/STAT, and cardiac disease prognosis." (PMID 41465371, 2025). "Multivariate analysis confirmed BMI, SFRP5, WNT5a, and JAK as independent predictors of cardiac disease, suggesting their potential as prognostic biomarkers." (PMID 41465371, 2025).
heart (1 paper, 2022). "Previous studies have confirmed that SFRP5 plays a protective role in diabetic heart injury." (PMID 35506262, 2022).
SFRP5 also shares sentences with these, for which no sentence is quoted: Impaired glucose tolerance (4 papers); prediabetes (3); acute myocardial infarction (2); asthma (2); inflammation (2); Myocardial fibrosis (2); rheumatoid arthritis (2); Arrhythmia (1); atrial fibrillation (1); cardioembolic stroke (1); cardiomyopathy (1); chondrosarcoma (1); chronic obstructive pulmonary disease (1); Cirrhosis (1); colorectal polyps (1); coronary atherosclerosis (1); craniorachischisis (1); dyslipidaemia (1); end-stage renal disease (1); fibrosis (1); hyperlipidemia (1); invasive breast carcinoma (1); liver cirrhosis (1); lymph node metastasis (1); obstructive sleep apnea☆☆☆ (1); oral squamous cell carcinoma (1); pancreatic cancer (1); pleura mesothelioma (1); polycystic ovary syndrome (1); psoriasis (1).
A further 7 diseases each share a sentence with SFRP5 in 1 paper.